INS (insulin)
Diseases named in the same sentence as INS in open-access papers (continued):
Sharing a sentence is not in itself a finding about the gene and the disease.
Insulin resistance (continued). "The endothelial dysfunction is suggested to be induced by PreDM pathophysiological factors such as lipid accumulation, insulin resistance, and impaired insulin secretion." (PMID 38203642, 2023). "For Zucker diabetic rats, significant increment in miR-29a expression weakened the activation degree of the insulin signaling pathway, indicating that the miR-29a expression level was closely related to insulin resistance." (PMID 37091861, 2023). "Adiponectin is responsible for sensitizing the body’s tissues to insulin, but large amounts of adipose tissue counterintuitively leads to a lower level of circulating adiponectin and perpetuates insulin resistance." (PMID 36830032, 2023). "Another suggested mechanism for how elevated TG leads to elevated PWV emphasizes its effect on insulin; high levels of triglycerides can interfere with insulin signaling, making cells less responsive to the hormone (i.e., insulin resistance)." (PMID 38455933, 2023). "Taken together, these findings suggest that GH and its receptor are required for the appropriate insulinotropic adaptation (β‐cell hyperplasia and increased compensatory insulin secretion) during the development of obesity and insulin resistance." (PMID 36480511, 2023). "Gestational diabetes is believed to result from inadequate insulin secretion failing to compensate for the degree of pregnancy insulin resistance." (PMID 37439859, 2023). "Obese and inactive subjects are more prone to imbalanced insulin homeostasis, and unhealthy dietary patterns can lead to hyperinsulinemia and insulin resistance (IR)." (PMID 36617570, 2023). "While insulin stimulates chondrocyte proliferation, one study found that its elevated serum levels (i.e., hyperinsulinemia) seen in insulin resistance, in fact, inhibited chondrocyte differentiation and maturation." (PMID 37629507, 2023). "Recently, CNS insulin resistance has been shown to play a role in the progress of dementia and AD due to the reduced CSF-to-plasma insulin ratio which hampers the transport of insulin across the BBB." (PMID 36674852, 2023). "Existing research suggests that ER stress can lead to the upregulation of PERK, promoting islet β-cell apoptosis, inhibiting insulin secretion, and inducing insulin resistance." (PMID 37978556, 2023). "The phosphorylated JNK (p-JNK) and IKK1/1KK2 further attenuate IRS-1 S307 residue phosphorylation, thereby suppressing insulin signaling activation to induce insulin resistance." (PMID 37555019, 2023). "L-DE-71 exposed females showed fasting hyperglycemia, glucose intolerance, insulin resistance, decreased plasma insulin, and elevated hepatic endocannabinoids." (PMID 37008952, 2023). "In the context of obesity and insulin resistance, EV-derived miRNAs functionally bridge major metabolic organs, including the adipose tissue, skeletal muscle, liver, and pancreas, to regulate insulin secretion and signaling." (PMID 37501663, 2023). "Lots of people believe that insulin resistance and diminished insulin signaling in the brain play a role in glucose hypometabolism." (PMID 36793541, 2023). "FBS, hemoglobin A1C (HbA1C), insulin activity, and Homeostatic Model Assessment for Insulin Resistance (HOMA-IR) significantly differed between the groups (p<0.0001)." (PMID 38107710, 2023). "These conditions also led to an insulin resistance state, which was observed by the increased levels of fasting serum glucose and insulin, and was confirmed by HOMA-IR and QUICKI." (PMID 36678606, 2023). "The accumulation of lipids in peripheral tissues contributes to the induction of insulin resistance, defined as an inability of insulin to adequately promote peripheral glucose disposal, suppress lipolysis, and decrease hepatic glucose output." (PMID 37153211, 2023). "Continued hyperinsulinemia appears to desensitize insulin signaling in skeletal muscle, hepatocytes, and adipocytes, further exacerbating systemic insulin resistance." (PMID 37242206, 2023).
Insulin resistance (continued). "It is important to note that NO production can be stimulated by insulin, whereas insulin resistance leads to impaired NO production." (PMID 37189834, 2023). "Over time, this can lead to a state of hyperinsulinemia (high levels of insulin in the blood), which can further exacerbate insulin resistance and contribute to the development of T2D." (PMID 37047308, 2023). "miR-499-5p affects insulin signaling and it has been found to be decreased in the liver and circulation during insulin resistance." (PMID 37371692, 2023). "While impairments in peripheral tissue insulin signalling have a well-characterized role in the development of insulin resistance and type 2 diabetes (T2D), the specific mechanisms that contribute to these impairments remain debatable." (PMID 37153211, 2023). "Taken together, sucralose augmented HFD-induced insulin resistance in mice, and interrupted insulin signals through a T1R3-ERK1/2-dependent pathway in the liver." (PMID 37375718, 2023). "Fasting insulin decreased from 16.8 uIU/L to 11.2 uIU/L (p < 0.01), concurrent with significantly reduced insulin resistance." (PMID 37986940, 2023). "Insulin resistance (IR) is an insulin resistance syndrome in which the peptide hormone insulin has a physiologic effect on peripheral target tissues that is less than predicted, resulting in hyperinsulinemia, the characteristic feature of IR." (PMID 36751233, 2023). "Previous Mendelian randomized analyses, systematic reviews, and meta-analyses have advocated the association between insulin resistance and CHD by altering vascular wall responses for insulin and promoting atherosclerosis." (PMID 37542255, 2023). "Unraveling the predominant site of insulin resistance will allow the use of novel, targeted, tissue-specific insulin-sensitizing agents in patients undergoing ADT." (PMID 36763576, 2023). "As a result, inflammation blocks insulin signaling pathways, which reduces the body’s sensitivity to insulin and increases the chance of developing insulin resistance." (PMID 36678130, 2023). "Insulin resistance and its associated abnormalities are important risk factor for development of complication in people with obesity so early detection and intervention are important, previous studies have reported that a diet that increased insulin level may increase metabolic risk factors." (PMID 37226148, 2023). "At night, the higher levels of insulin resistance led to a greater demand for insulin, which was needed to metabolize large amounts of blood glucose." (PMID 36986139, 2023). "Conversely, the influence of insulin on dopamine release is lost in rats on a HF-HS diet, consistent with peripheral and central insulin resistance seen in human obesity." (PMID 36979453, 2023). "This suggests a role of zinc in glucose metabolism possibly involving both insulin secretion and insulin resistance." (PMID 36693633, 2023). "This chronic state of inflammation imperils the intricate machinery of insulin signaling, fosters insulin resistance, and thereby precipitates the onset of diabetic complications." (PMID 37986076, 2023). "In this regard, metformin, which is a drug known to enhance insulin sensitivity, reduced insulin resistance and hepatic steatosis in a NAFLD mouse model induced by HFD by promoting autophagy in a TFEB-dependent manner." (PMID 37876013, 2023). "The role of mTOR/p706SK signaling has been confirmed by many other groups as a critical mechanism involved in the induction of insulin resistance in insulin-sensitive tissues (muscle, fat and liver)." (PMID 36982168, 2023). "Initially, T2DM begins as insulin resistance, characterized by a diminished insulin response leading to impaired action in metabolically active organs and tissues such as the liver, muscle, and adipose." (PMID 38192911, 2023). "The condition that insulin target tissues are weakly sensitive to metabolic reactions related to insulin is defined as insulin resistance (IR)." (PMID 36747129, 2023).
Insulin resistance (continued). "A high intake of junk foods can lead to insulin resistance, a condition where the body’s cells become less responsive to insulin." (PMID 37891760, 2023). "In hepatocytes experiencing insulin resistance, the regulation of insulin signal transduction becomes compromised, and the PI3K/Akt signaling pathway, downstream of the insulin receptor, is suppressed." (PMID 37759297, 2023). "Insulin resistance refers to the reduced responsiveness of the body to the physiological effects of insulin." (PMID 37534205, 2023). "This process promotes muscle and hepatic insulin resistance and impairs insulin secretion by pancreatic β-cells." (PMID 37780623, 2023). "T2D is marked by insulin resistance and the productivity dysfunction of insulin secreted from β cells of the pancreas." (PMID 38137918, 2023). "The increase in plasma resistin concentration impairs insulin sensitivity and decreases glucose tolerance in mice, and plays a significant role in human obesity-induced insulin resistance." (PMID 36998471, 2023). "Insulin resistance, compensatory hyperinsulinism, and an increase in ovarian androgenic hyperresponsiveness to circulating insulin are all directly related to hyperandrogenism and anovulation." (PMID 36751233, 2023). "Insulin resistance is typically defined as a reduced sensitivity or responsiveness to the metabolic actions of insulin." (PMID 37863941, 2023). "Because they have insulin resistance, lower early-phase insulin secretion prevents those with type 2 diabetes from being able to perform the metabolic mechanisms necessary for glucose uptake, further contributing to hyperglycemia and T2D." (PMID 37049602, 2023). "Nonetheless, the effects of ω-3 fatty acids on insulin resistance remain controversial with some reports indicating an improvement of insulin sensitivity upon their supplementation, whereas other studies fail to confirm this effect." (PMID 36979141, 2023). "Insulin resistance is a state in which higher than normal levels of circulating insulin are required to maintain glucose homeostasis and compensate for decreased insulin sensitivity of key organs involved in metabolic control – liver, muscle, and fat1." (PMID 37291194, 2023). "Peripheral insulin resistance, hyperglycemia, inflammation, and gluconeogenesis in the liver increased the need for insulin production, increasing oxidative stress and ER stress in the beta cell." (PMID 37280499, 2023). "In peripheral insulin resistance, there is abnormal glucose uptake and metabolism by the major target tissues of insulin, skeletal muscle, and adipose tissue." (PMID 38292764, 2023). "Our study emphasizes the applicability of both HOMA-IR and insulin-free indirect insulin resistance indices in PTDM prediction." (PMID 38068348, 2023). "Compared to WT mice, apoA-IV deficiency displayed glucose intolerance and elevated insulin levels, according to the data of the glucose tolerance test, and increased HOMA-IR values at fasting, suggesting possible insulin resistance." (PMID 37960308, 2023). "Insulin resistance manifests itself through the inadequate ability of insulin to reuptake glucose in the tissues of skeletal muscle, adipose tissue, and the liver." (PMID 38139115, 2023). "Although macrophages have been found to produce pro-inflammatory cytokines that enhance insulin resistance, experimental evidence demonstrate that macrophages also secrete and respond to anti-inflammatory cytokines, enhancing insulin sensitivity." (PMID 36994095, 2023). "The primary outcomes were body fat percentage and cardiorespiratory endurance and the secondary outcomes included blood glucose level, insulin level, homeostasis model assessment of insulin resistance (HOMA-IR), muscle strength, and cholesterol level." (PMID 38002444, 2023). "Normally, through the PI3K pathway, insulin controls the deterioration of apoB; however, under insulin resistance, this process is inadequate." (PMID 37664840, 2023).
Insulin resistance (continued). "In the diabetic db/db mice, hyperglycemia, which was accompanied by an increase in insulin secretion in diabetic mice, was significantly reduced by AH treatment, resulting in the alleviation of β-cell overcompensation and insulin resistance." (PMID 37895834, 2023). "Insulin resistance refers to the decreased sensitivity of cells to insulin, resulting in decreased glucose uptake and compensatory secretion of insulin, which is manifested as hyperinsulinemia." (PMID 38003436, 2023). "Increased fasting insulin levels due to a reduction in insulin receptors leads to insulin resistance, which manifests as increased HOMA-IR." (PMID 37834276, 2023). "GCs produce dysregulation of glucose-induced insulin release and insulin resistance by activating specific receptors that decrease the uptake of glucose in the peripheral tissues and increase the hepatic production of glucose." (PMID 37894792, 2023). "Reduced sensitivity of peripheral tissues to insulin and lower than normal biological efficacy of insulin is known as insulin resistance." (PMID 37957709, 2023). "Cellular insulin resistance is resulted from the accumulation of abnormal lipids in insulin-sensitive tissues like liver, muscles, and adipose tissue." (PMID 37441501, 2023). "The pathophysiology of T2D is characterized by elevated blood glucose levels due to insulin resistance (IR) and insufficient insulin secretion by the pancreas." (PMID 36771304, 2023). "Insulin resistance is identified as an impaired biological response to insulin stimulation of target tissues, mainly liver, muscle, and adipose tissue." (PMID 36904180, 2023). "There is strong evidence showing that an improvement in muscle mass and/or muscle strength improves insulin sensitivity and prevents insulin resistance." (PMID 38004100, 2023). "A significant reduction in fasting insulin and a trend towards a reduction in insulin resistance were identified in the metformin group compared with pre-treatment levels." (PMID 37108132, 2023). "Overexpressing Adgrf1 in the liver of STC-fed mice did not affect body weight, fasting glucose level, fasting insulin level, and homeostatic model assessment for insulin resistance (HOMA-IR)." (PMID 37580962, 2023). "Decreased insulin-stimulated translocation of GLUT4 to the skeletal muscle surface, and/or decreased expression of GLUT4, are well-accepted causes of insulin resistance." (PMID 37371869, 2023). "By inhibiting Kallikrein 7, vaspin blocks insulin degradation, resulting in reduced insulin resistance and improved glucose tolerance." (PMID 36981906, 2023). "Hyperinsulinemia is considered to be an important risk factor for the development of T2D and is a condition in which chronic exposure to elevated insulin levels often contributes to insulin resistance, ultimately leading to T2D." (PMID 38004101, 2023). "Matsuzaka's research demonstrates that manipulating fatty acid components by blocking Elovl6 can prevent insulin resistance, impaired insulin secretion and obesity-related diseases." (PMID 37100872, 2023). "Gut bacteria in T2DM elevated insulin resistance by decreasing insulin signaling and increasing glucagon signaling." (PMID 37298483, 2023). "Disposition index (early phase insulin secretion/homoeostasis model assessment of insulin resistance) was lowest in the PPM+ group (p = 0.02)." (PMID 37333553, 2023). "Although the mean baseline glycemia was within the normal range, the high HOMA index evidenced that it was achieved at the expense of a high insulin resistance accompanied by a low insulin sensitivity, as indicated by the QUICKI index." (PMID 38004218, 2023). "Insulin secretion is critical for glucose homeostasis, and increased levels of the precursor proinsulin relative to insulin indicate pancreatic islet beta-cell stress and insufficient insulin secretory capacity in the setting of insulin resistance." (PMID 36693378, 2023).
Insulin resistance (continued). "For example, despite strong support for the role of PRL in promoting insulin secretion in pregnancy, several studies show that high levels of PRL are associated with insulin resistance and/or hyperglycaemia, beta cell dysfunction and risk of GDM." (PMID 37049394, 2023). "An experimental study on mice has shown that insulin resistance appears as a result of induced disorders of the insulin signaling pathway in the liver, skeletal muscle, and adipose tissue and causes hyperinsulinemia, thereby leading to the development of T2D." (PMID 36902173, 2023). "Insulin resistance eventually leads to the compensatory secretion of excessive insulin by the body, manifesting hyperinsulinemia to maintain body glucose homeostasis." (PMID 37103360, 2023). "The global physiological effect of this differential signaling has been shown to involve altered insulin sensitivity such that maternal obesity leads to insulin resistance and maternal low protein leads to increased insulin sensitivity." (PMID 37855320, 2023). "Many lines of evidence have shown that the chronic activation of intracellular proinflammatory pathways within insulin target cells can lead to insulin resistance." (PMID 36769405, 2023). "In particular, estradiol protects the functionality of the pancreatic beta cells and prevents apoptosis while lowering insulin resistance and increasing insulin sensitivity." (PMID 36833469, 2023). "Insulin resistance is a complex pathological condition characterized by reduced insulin-stimulated glucose uptake in adipocytes and skeletal muscle, impaired physiological suppression of hepatic gluconeogenesis and lipolysis, and impaired glycogen synthesis." (PMID 37121975, 2023). "Black women had increased fasting insulin levels, homeostatic model assessment of insulin resistance (HOMA-IR) scores, and systolic blood pressure when compared with White women." (PMID 36702345, 2023). "Insulin resistance develops owing to high levels of insulin secretion, which leads to the development of type 2 diabetes." (PMID 37305117, 2023). "This down regulation of HSPs is associated with insulin resistance (IR) and interventions which induce the heat shock response (HSR) help to increase the insulin sensitivity." (PMID 37594932, 2023). "The objective of this study is to assess the impact of a 3-month daily intake of 4 grams of ω-3PUFA on insulin sensitivity in individuals with obesity who have previously been diagnosed with insulin resistance and systemic inflammation." (PMID 38024342, 2023). "METS-IR, a non-insulin-based insulin resistance, was found to be a higher concordance with HEC and has been proven to be associated with multiple risk factors of CVD and cardiovascular events." (PMID 37461067, 2023). "There is also a growing body of evidence suggesting that chronic sleep deprivation can impact insulin levels and contribute to insulin resistance." (PMID 38054122, 2023). "Several studies using HOMA-IR revealed a correlation between exercise and insulin sensitivity, where the authors found a significant decrease in insulin resistance in the PCOS Group." (PMID 37432289, 2023). "Model parameter k was weakly correlated with the baseline insulin concentration, insulin resistance, insulin sensitivity, and glucose disposition (p < 0.05)." (PMID 36771243, 2023). "Therefore, having an iron-overload influence on the expansion of visceral adipose tissue independently of insulin sensitivity suggests that correcting early iron excess could have a preventive effect on insulin-resistance progression associated with visceral adiposity." (PMID 36902180, 2023). "1,25‐dihydroxy vitamin D (1,25OHD), a physiologically functional version of vitamin D, may improve insulin activity by boosting insulin manufacturing and secretion, elevating insulin receptor transcription, or suppressing pro‐inflammatory cytokines that are thought to cause insulin resistance." (PMID 37701195, 2023).